ALPK1 (alpha kinase 1)
Diseases named in the same sentence as ALPK1 in open-access papers (continued):
Sharing a sentence is not in itself a finding about the gene and the disease.
oral cancer (5 papers, 2022 to 2024). "ALPK1 expression was abnormal in malignant oral cancer cell lines compared to precancerous oral epithelial cells and normal oral epithelial cells." (PMID 36139553, 2022). "HAR1A acted as a tumor suppressor for oral cancer by regulating the ALPK1/BRD7/myosin IIA axis in oral cancer." (PMID 35740511, 2022). "TNF-α was decreased in ALPK1-depleted metastatic oral cancer cells." (PMID 36139553, 2022). "In this systematic review, ALPK1 was discovered to upregulate myosin IIA in monosodium-urate-treated cells, whereas ALPK1 was found to downregulate myosin IIA in oral cancer cells." (PMID 36139553, 2022). "In the nucleus of cancer cells, HAR1A functioned upstream of the signaling pathway, and knockdown of HAR1A promoted ALPK1 expression and downregulated myosin IIA and BRD7, leading to inflammation and oral cancer progression." (PMID 36139553, 2022). "HAR1A is a tumor suppressor, and in oral cancer patients, knockdown of HAR1A promotes the expression of ALPK1 and leads to oral cancer progression." (PMID 35757472, 2022). "In oral cancer cells and monocytes, the expression of TNF-α and CCL2 was increased after HAR1A knockdown and decreased after ALPK1 knockdown." (PMID 36139553, 2022). "HAR1A was shown to have a tumour suppressor role in oral cancer via interaction with Alpha Kinase-1 (ALPK1), and in non-small cell lung cancer via modulation of the Signal Transducers and Activator of Transcription 3 (STAT3) pathways." (PMID 39602392, 2024). "In Chen’s qualitative study, ALPK1 was rarely expressed in noncancerous tissues but was present in the keratinocyte layer and was strongly expressed in oral cancer tissues." (PMID 36139553, 2022).
leukemia (4 papers, 2022 to 2025). A malignant (clonal) hematologic disorder, involving hematopoietic stem cells and characterized by the presence of primitive or atypical myeloid or lymphoid cells in the bone marrow and the blood. "Li and Ji identified ALPK1, together with other genes, as a prognostic risk factor for leukemia." (PMID 36139553, 2022). "We therefore propose the ADP-heptose–ALPK1 axis as a potential therapeutic target to prevent CHIP progression to overt leukaemia and immune-related conditions." (PMID 40269158, 2025). "A recent paper has also linked the ADP-heptose-ALPK1 axis to ageing and expansion of rare leukemic cells, thus suggesting ALPK1 as a potential target to prevent progression of clonal haematopoiesis of indeterminate potential (CHIP) to overt leukemia and other related immune conditions." (PMID 40925900, 2025). "However, ALPK1 expression was also increased in individuals without DNMT3A mutations, suggesting that activated TIFAsomes may involve other leukaemia driver mutations." (PMID 40269158, 2025).
lung carcinoma (4 papers, 2016 to 2025). "According to the collected Cosmic database, the ratio of ALPK1 point mutations accounted for 2.29% of all the mutations in the lung cancer samples and 3.71% of those in the cancer of the large intestine samples." (PMID 27283888, 2016). "Additionally, in both Lovo colorectal and A549 lung cancer cells with enhanced and depleted expression of ALPK1, the encoded ALPK1 could exert its activity on cell migration without interfering with cell viability." (PMID 27283888, 2016). "These interesting phenomena implied that these SNPs might be more highly related to colorectal and lung cancers in the Taiwanese population, in addition to suggesting the new insight that ALPK1 may modulate colorectal and lung cancer susceptibility or prognosis." (PMID 27283888, 2016). "ALPK1 triggers activation of the inflammatory NF-κB signaling pathway and plays a vital role in the pathogenesis of lung cancer." (PMID 41144480, 2025). "Lately, however, there have been no studies that have elucidated the function of ALPK1 in colorectal and lung cancer cells." (PMID 27283888, 2016).
diabetic nephropathy (3 papers, 2019 to 2023). "ALPK1 was therefore determined to be a mediator involved in diabetic-nephropathy-induced upregulation of CCL2 and CCL5 chemokines." (PMID 36139553, 2022). "ALPK1 is a mediator of CCL2 and CCL5 chemokine, and upregulation of NF-κβ is associated with the induction of diabetic nephropathy." (PMID 36139553, 2022). "The TG‐STZ mice were employed for investigating the role of ALPK1 in diabetic nephropathy pathogenesis." (PMID 31557402, 2019). "Alpha‐kinase 1 (ALPK1) is a master regulator in inflammation and has been proved to promote renal fibrosis by promoting the production of IL-1β in diabetic nephropathy (DN) mice." (PMID 36732854, 2023). "Our data suggest that ALPK1 is a potential mediator for CCL2 and CCL5 chemokines induction involving in ALPK1‐mediated accelerated diabetic nephropathies." (PMID 31557402, 2019). "ALPK1 is a mediator for CCL2 and CCL5 chemokine up‐regulation involving in diabetic nephropathies induction." (PMID 31557402, 2019).
Hyperglycemia (3 papers, 2021 to 2023). An increased concentration of glucose in the blood. "Previous study has also proved that ALPK1 enhanced production of IL-1β in the kidney of experimental models of hyperglycemia and resulted in the induction of fibrotic renal injury." (PMID 36732854, 2023). "The mechanism of how hyperglycemia activates ALPK1 and how ALPK1-NF-κB signal pathway activates GSDMD-related canonical pyroptosis are unclear." (PMID 36732854, 2023). "Considering the critical regulatory role of ALPK1 in inflammation under hyperglycemia conditions, it is reasonable to assume that ALPK1 participates in the development of renal injury in hyperglycemic condition." (PMID 36732854, 2023). "Hyperglycemia was induced in wild-type and ALPK1 transgenic mice by intraperitoneal injection of streptozotocin." (PMID 36139553, 2022). "Findings from experimental models of hyperglycemia suggest that TGF-β1, IL-1β, renin, and ALPK1 levels in the kidney or blood is associated with ALPK1-induced fibrotic kidney injury." (PMID 36139553, 2022). "In conclusion, hyperglycemia activates ALPK1 in renal TECs, leading to phosphorylation of NF-κB, which could contribute to release of the N-terminal domain of GSDMD after cleavage by caspase-1." (PMID 36732854, 2023). "A recent paper has shown that Alpk1-overexpressed C57BL/6 mice exhibited a decreased insulin level and severe hyperglycaemia than wild type mice after streptozotocin (STZ) treatment, suggesting that Alpk1 might participate in the destruction of pancreatic beta cells." (PMID 34621265, 2021).
Nephropathy (3 papers, 2019 to 2022). A nonspecific term referring to disease or damage of the kidneys. "ALPK1 is known to be associated with kidney disease through association studies, and its expression in animal models can regulate the release of the chemokines CCL2 and CCL5 in kidney cells." (PMID 35505381, 2022). "One study identified mediators contributing to the effects of ALPK1 in the induction of nephropathy." (PMID 36139553, 2022). "The increase in ALPK1, mainly in diabetic animal and human kidney cell models, leads to accelerated fibrotic nephropathy by enhancing the production of renin, TGF-β1, and IL-1β." (PMID 36139553, 2022). "The aim of this study was to identify the mediators contributing to ALPK1 effect involving in nephropathies induction." (PMID 31557402, 2019). "Accelerated fibrotic nephropathies were observed in hyperglycaemic mice with up‐regulated ALPK1." (PMID 31557402, 2019).
skin cancer (3 papers, 2022 to 2025). "ALPK1 is involved in the progression of breast, lung, colorectal, oral, and skin cancer as well as lymphoblastic leukemia." (PMID 36139553, 2022).
breast carcinoma (2 papers, 2016 to 2022). "The relevance of ERN1 and ALPK1 as potential therapeutic targets was reinforced by an effect of the respective siRNAs on colony formation of other breast cancer cell lines." (PMID 27829216, 2016). "In vivo, ERN1- or ALPK1-deficient breast cancer cells were found to be less tumorigenic than those without these deficiencies." (PMID 36139553, 2022). "We show that inhibition of ERN1 and ALPK1 restricts anchorage-independent spheroid formation of an additional TNBC cell line and two luminal breast cancer cell lines." (PMID 27829216, 2016).
breast tumor (2 papers, 2019 to 2022). "These were a frameshift variant on ALPK1, a gene with downregulated expression in lung and colorectal tumors, and a frameshift variant on ST18, a gene with tumor-suppressing activity in breast tumors." (PMID 36077770, 2022). "It was reported that knocking down either ERN1 or ALPK1 could push bipotential breast tumor-initiating cells towards the luminal fate." (PMID 31636652, 2019).
glioma (2 papers, 2024 to 2025). A benign or malignant brain and spinal cord tumor that arises from glial cells (astrocytes, oligodendrocytes, ependymal cells). "Elevated levels of ALPK1 expression were associated with heightened infiltration of immune cells in several cancer types, indicating its potential significance in modulating the immune microenvironment of gliomas and positioning it as a promising target for forthcoming immunotherapeutic strategies." (PMID 39845963, 2024). "Studies have shown that ALPK1 can affect the expression of immune-related genes, thereby changing the tumor microenvironment and affecting the development of glioma." (PMID 39845963, 2024). "By stratifying the combined glioma dataset according to the median expression level of ALPK1, we categorized it into groups of high and low expression." (PMID 39845963, 2024). "Comparative analysis of expression levels among different cell lines revealed that ALPK1 is significantly overexpressed in glioma cell lines (p < 0.05)." (PMID 39845963, 2024). "A comprehensive analysis across multiple cancers revealed a notable relationship between the ALPK1 gene and different immune checkpoints, alongside its link to the prognosis of patients with glioma." (PMID 39845963, 2024). "Furthermore, research experiments suggest that ALPK1 is vital for enhancing the proliferation of glioma cells." (PMID 39845963, 2024). "Therefore, our findings suggest that ALPK1 plays a critical role in promoting glioma cell proliferation." (PMID 39845963, 2024). "integrated scRNA-seq with machine learning techniques to uncover the role of ALPK1 in shaping tumor immune heterogeneity and regulating the TGF-β signaling pathway in glioma." (PMID 40777122, 2025). "There is currently a lack of studies investigating the role of ALPK1 in glioma cells; thus, we selected this gene from our model for experimental validation." (PMID 39845963, 2024).
inflammatory bowel disease (2 papers, 2018 to 2020). A spectrum of small and large bowel inflammatory diseases of unknown etiology. "Cd14 and Alpk1 both encode pathogen recognition receptors and are known candidate genes for affecting severity in inflammatory bowel diseases." (PMID 32076438, 2020).
lymphoblastic leukemia (2 papers, 2022 to 2023). "After 70 months of follow-up, ALPK1, ACTN4, CALR, and ZNF695 were identified as potential prognostic risk factors for adult acute lymphocytic leukemia in the overall survival analysis." (PMID 36139553, 2022). "ALPK1, ACTN4, CALR, ZNF695, and FBXL5 were identified as novel prognostic genes in relapsed acute lymphoblastic leukemia." (PMID 36139553, 2022).
Obesity (2 papers, 2015 to 2022). Accumulation of substantial excess body fat. "Interestingly, previous studies have identified ALPK1 (rs4833407), 100kb proximal to ZGRF1, to be associated with obesity in European populations." (PMID 26599207, 2015).
oral squamous cell carcinoma (2 papers, 2022 to 2023). "ALPK1-deficient oral squamous cell carcinoma metastasis leads to reduced TNF-α production in cancer cells." (PMID 36139553, 2022). "Similarly, an increased expression of ALPK1 was found to facilitate the progression of oral squamous cell carcinoma (ALPK1 has a function as an oncogene)." (PMID 37317291, 2023).
renal fibrosis (2 papers, 2023 to 2024). A final common manifestation of a wide variety of chronic kidney diseases characterized by glomerulosclerosis and tubulointerstitial fibrosis. "Previous researches have confirmed ALPK1 promotes renal fibrosis in mice by promoting the production of pro-inflammatory cytokines IL-1β, IL-8 and TNF-α." (PMID 36732854, 2023). "Western blot analysis showed increased expressions of ALPK1, phospho-NF-κB P65, GSDMD-NT, and IL-1β in renal tissues of DN mice and HK-2 cells, accompanied with increased renal fibrosis-related proteins (FN, α-SMA) and macrophages infiltration in interstitial areas." (PMID 36732854, 2023).
retinal degeneration (2 papers, 2022 to 2025). Degeneration of the retina. "At 16 weeks, mice did not have an increase in spleen size or weight and mice did not exhibit visual decline or evidence of retinal degeneration due to Alpk1 mutation at up to 12 months of age." (PMID 35868845, 2022).
Campylobacter enteritis (1 paper, 2023). "Induction of NF-κB and subsequent immune responses by an alpha-kinase-1-dependent (ALPK1) signaling pathway is described as more specific to Campylobacter enteritis." (PMID 36941439, 2023).
enteritis (1 paper, 2021). Inflammation of the small intestine. "This classifies ADP-heptose and/or related heptose phosphates as a major virulence factor that may contribute to acute human enteritis by activating the proinflammatory ALPK1-NF-κB pathway." (PMID 34339468, 2021).
glioblastoma multiforme (1 paper, 2024). "In both glioblastoma multiforme (GBM) and lower-grade glioma (LGG), ALPK1 showed a significant positive association with four immune checkpoints: PD-L1 (CD274), CTLA-4, LAG-3, and PD-1 (PDCD1)." (PMID 39845963, 2024).
influenza (1 paper, 2025). An acute viral infection of the respiratory tract, occurring in isolated cases, in epidemics, or in pandemics; it is caused by serologically different strains of viruses (influenzaviruses) designated A, B, and C, has a 3-day incubation period, and usually lasts for 3 to 10 days. "Whether ALPK1 activation can modulate the activity of such channels is an intriguing area for future study, especially given the potential for bacterial metabolite sensing to exacerbate STING-mediated inflammation during viral infections like influenza." (PMID 40631099, 2025).
migraine (1 paper, 2019). "ALPK1 encodes Alpha Kinase 1, which may play roles in inflammation and intracellular trafficking, although its function is poorly defined, and it is not yet understood the how mutations in the protein would contribute to migraine." (PMID 31226929, 2019).
neutropenia (1 paper, 2025). A decrease in the number of neutrophils found in the blood. "In addition to the previously reported neutrophil dysfunction in ALPK1-mutated patients and its association with disease activity, our study highlights neutropenia as a notable manifestation." (PMID 41235249, 2025).
Optic neuropathy (1 paper, 2025). "This case also highlights the importance of including ALPK1 in genetic panels for optic neuropathies, retinal disorders, and unexplained arthropathies to improve diagnosis and treatment strategies." (PMID 41269507, 2025).
pericarditis (1 paper, 2024). An inflammatory process affecting the pericardium. "Eleven variants were located in genes already associated with recurrent pericarditis (NLRP3, TNFRSF1A and MEFV) and five in inflammation/immunodeficiency-related genes (IFIH1, NFKBIA, JAK1, NOD2 and ALPK1)." (PMID 39347728, 2024).
pneumonia (1 paper, 2022). An acute, acute and chronic, or chronic inflammation focally or diffusely affecting the lung parenchyma, caused by an infection in one or both of the lungs (by bacteria, viruses, fungi, or mycoplasma.). "In the present study, GmhB was dispensable for normal inflammation during pneumonia as determined by immune cell recruitment and cytokines signatures associated with ALPK1/TIFA/NF-κB signaling." (PMID 35762751, 2022).
Sepsis (1 paper, 2024). Sepsis is defined as life-threatening organ dysfunction caused by a dysregulated host response to infection. "We identified significant upregulation of NTSR1, BCL6, ZDHHC19, MGLL, and ALPK1 in sepsis compared to healthy individuals, while VAV2 and SATB1 were significantly downregulated in sepsis." (PMID 38167131, 2024). "Additionally, bulk RNA analysis revealed significant increases in NTSR1, BCL6, ZDHHC19, MGLL, and ALPK1 in sepsis, and significant decreases in VAV2 and SATB1 in sepsis; FCHO1 showed a significant decrease in sepsis patients who did not survive compared to those who survived at 28 days." (PMID 38167131, 2024). "The observed significant upregulation of NTSR1, BCL6, ZDHHC19, MGLL, and ALPK1 in sepsis compared to healthy individuals, along with the notable downregulation of VAV2 and SATB1 in sepsis, provides a comprehensive picture of the altered gene expression landscape during sepsis." (PMID 38167131, 2024).
synovitis (1 paper, 2024). Inflammation of a synovial membrane. "Our study found that ALPK1 knockout mice exhibited decreased synovial cell layers, stromal cell density and inflammatory cell infiltration, as well as significantly lower synovitis scores, indicating that ALPK1 could promote the development of TMJ synovitis." (PMID 38494837, 2024).
triple-negative breast carcinoma (1 paper, 2022). An invasive breast carcinoma which is negative for expression of estrogen receptor (ER), progesterone receptor (PR), and human epidermal growth factor receptor 2 (HER2). "Strietz noted that triple-negative breast cancer cells lacking ALPK1 or ERN1 were less tumorigenic than those not lacking them, suggesting their role in the same pathway." (PMID 36139553, 2022).